NLRP3 (NLR family pyrin domain containing 3)
Diseases named in the same sentence as NLRP3 in open-access papers (continued):
Sharing a sentence is not in itself a finding about the gene and the disease.
status epilepticus (10 papers, 2014 to 2025). Status epilepticus is defined as a continuous seizure lasting more than 30 min, or two or more seizures without full recovery of consciousness between any of them. "Pilocarpine-induced status epilepticus resulted in a significant upregulation of the inflammasome gene Nlrp3 in both brain regions." (PMID 41009625, 2025). "When NLRP3 is inhibited, the anti-epileptic and neuroprotective effects are observed after amygdala kindling induces status epilepticus." (PMID 35624482, 2022). "In a rat amygdala kindling-induced status epilepticus (SE) model, the levels of IL-1β, caspase-1 and NLRP3 were found to be increased, and neuroprotection was observed when NLRP3 inflammasome was knocked down in vivo by small interfering RNAs." (PMID 34112082, 2021). "Some scholars have found that prednisone can inhibit NLRP3 to reduce immune demyelination and that inhibiting NLRP3 can alleviate brain injury from status epilepticus." (PMID 32116990, 2019). "IL-1β and NLRP3 levels increased after amygdala kindling-induced status epilepticus, and inhibition of NLRP3 provided neuroprotection in rats following status epilepticus." (PMID 28109197, 2017). "NLRP3, nucleotide binding and oligomerization domain-like receptor family pyrin domain-containing 3; SE, status epilepticus; sec, seconds; SRS, spontaneous recurrent seizures." (PMID 25516224, 2014). "A study proved that the TRPV4 specific inhibitor HC067047 could block the increases in NLRP3 and caspase-1 following pilocarpine-induced status epilepticus in mice, and the experimental results are consistent with our data." (PMID 35093118, 2022). "Overexpression of GPR120 significantly alleviated epileptic activity, reduced neuronal death after status epilepticus (SE), downregulated the expression of IL-1β, IL-6, IL-18, and pyrin domain-containing protein 3 (NLRP3) inflammasome, whereas knockdown GPR120 showed the opposite effect." (PMID 35624482, 2022). "For this reason, we used NLRP3 gene knockout mice to construct a status epilepticus model." (PMID 32116990, 2019). "This study aimed to investigate the role of the NLRP3 inflammasome in neuroinflammation, spontaneous recurrent seizures (SRS) and hippocampal neuronal loss in rat brain following amygdala kindling-induced status epilepticus (SE)." (PMID 25516224, 2014).
synovitis (10 papers, 2014 to 2023). Inflammation of a synovial membrane. "The NLRP3 inflammasome plays a unique role in the pathogenesis of synovitis, which is an important mechanism underlying OA pathogenesis." (PMID 34085175, 2021). "The associations of NLRP3 with OA risk factors, cartilage degeneration, synovitis and OA pain are depicted in detail." (PMID 33637064, 2021). "The NLRP3 inflammasome is also known to be associated with synovitis." (PMID 34085175, 2021). "The TCM monomer/active ingredient, decoction, external ointment, and acupuncture regulating NLRP3 inflammasomes are helpful to alleviate synovitis in KOA." (PMID 37065495, 2023). "Targeting the NLRP3 inflammasome can be a novel approach and therapeutic direction for the treatment of synovitis in KOA." (PMID 37065495, 2023). "The pathophysiology of synovitis in KOA can be further understood by analysis of the role of the NLRP3 inflammasome." (PMID 37065495, 2023). "The NLRP3 inflammasome plays a significant role in the pathogenesis of synovitis in KOA, and innate immunity is activated during the pathogenesis of this condition." (PMID 37065495, 2023). "Our study demonstrated that NLRP3 inflammasome-mediated pyroptosis was involved in rat TMJOA synovitis." (PMID 36466156, 2022). "In our study, we explored the role of NLRP3 inflammasome in TMJOA synovitis and the therapeutic potential of caspase-1 and NLRP3 inhibitors." (PMID 36466156, 2022). "The result demonstrated that NLRP3 inflammasome-mediated pyroptosis was positively correlated with TMJOA synovitis in vivo." (PMID 36466156, 2022). "Given that IMP has long been used to treat KOA, its effects on NLRP3 inflammasome cascade-induced synovial fibrosis and synovitis in KOA rats were assessed." (PMID 34847824, 2021). "NLRP3 inflammasome has been reported to be involved in hydroxyapatite-induced synovitis of the knee, and the application of NLRP3 inhibitor MCC950 can also significantly ameliorate RA." (PMID 34777685, 2021). "Studies in an air pouch model of synovitis also confirmed the activation of NLRP3/ASC/caspase 1 by hydroxyapatite crystals and supported a role in controlling neutrophil infiltration." (PMID 25175678, 2014). "The activation of NLRP3 inflammasome can induce the secretion of proinflammatory cytokines IL-1β and IL-18, leading to the aggravation of downstream inflammatory response and accelerating the occurrence of synovitis in KOA." (PMID 37065495, 2023). "In addition, Casticin can inhibit the activation of NLRP3 inflammasome in rats KOA model and FLS, indicating that Casticin alleviates MIA-induced synovitis in KOA by inhibiting the activation of HIF-1α/NLRP3 inflammasome." (PMID 37065495, 2023). "We proposed that the NLRP3-mediated pyroptosis is involved in the TMJOA synovitis and may aggravate the subsequent inflammation." (PMID 36466156, 2022). "The study identifies that NLRP3-mediated pyroptosis is closely related to TMJOA synovitis." (PMID 36466156, 2022). "Therefore, we proved that the NLRP3 inflammasome-mediated pyroptosis is involved in the process of TMJOA synovitis." (PMID 36466156, 2022). "We hypothesized that SDF-1 can decrease expression of the NLRP3 inflammasome and related proteins in synoviocytes from OA joints exhibiting synovitis and may have potential as a novel therapeutic target for synovitis in OA." (PMID 34085175, 2021). "In this study, we aimed to investigate whether vanillic acid (VA), a monomer derived from Chinese herbal medicines, could target NLRP3 inflammasome-related synovitis to reduce pain." (PMID 33658936, 2020). "Therefore, in this study, we observed the intervention effects of VA on NLRP3 inflammasome activation, synovitis, and KOA pain-related behaviors/mediator in vivo or in vitro." (PMID 33658936, 2020).
Thrombocytopenia (10 papers, 2021 to 2025). A reduction in the number of circulating thrombocytes. "Intriguingly, selective NLRP3 inhibitors have been shown to ameliorate platelet defects associated with DV, suggesting that the NLRP3 inflammasome may be a novel target for the treatment of Dengue-associated thrombocytopenia." (PMID 37108623, 2023). "Nevertheless, an investigation has indicated that ND stimulates platelets aggregation and pyroptosis to trigger thrombocytopenia, which is dependent on P-selectin-induced mitochondrial superoxide production and NLRP3 inflammasome activation." (PMID 37063905, 2023). "HS activated the NLRP3 inflammasome, which was induced by elevated levels of ROS, while the upregulated CD62P and thrombocytopenia triggered by NLRP3 inflammasome were attributed to the high mobility group box protein 1 (HMGB1) inplasma." (PMID 35945940, 2022). "Treatments of inhibitors against P-selectin, ROS and Nlrp3 inflammasome pathways ameliorated both ND-induced platelet activation in vitro and ND-induced thrombocytopenia in mice." (PMID 35444640, 2022). "We also unraveled the role of HMGB1 in inducing NLRP3 inflammasome activation, platelet activation, and thrombocytopenia in HS." (PMID 35945940, 2022). "In this experiment, we also found that inhibiting HMGB1 by EP and anti-HMGB1 neutralizing antibody down-regulated the activation of the NLRP3 inflammasome, platelet activation, and thrombocytopenia." (PMID 35945940, 2022). "In conclusion, this study preliminarily demonstrates that elevated extracelluar HMGB1 induced high levels of ROS via both TLR4 and RAGE receptors of platelets, which in turn participates NLRP3 inflammasome activation leading to thrombocytopenia in HS rats." (PMID 35945940, 2022). "The loss of NLRP3 also protected from sHLH-driven leukopenia, thrombocytopenia, and reduced lymphocytes but did not affect neutrophil numbers." (PMID 40632844, 2025). "In addition, challenges of NDs induced less platelet pyroptosis and displayed less thrombocytopenia in P-selectin (Selp-/-), Nlrp3 (Nlrp3-/-) and caspase-1 (Casp1-/-) mutants, as compared to the wild type mice." (PMID 35444640, 2022). "Blockers of P-selectin, ROS, and Nlrp3 inflammasome pathways could be considered as antidotes for ND induced platelet activation and thrombocytopenia." (PMID 35444640, 2022). "Unfortunately, whether HMGB1-induced activation of NLRP3 inflammasome is involved in platelet activation and thrombocytopenia in HS is to be elucidated." (PMID 35945940, 2022). "It is not known whether NOD-like receptor family pyrin domain containing 3 (NLRP3) inflammasome is activated in HS platelet, which, in turn, induces platelet activation and thrombocytopenia." (PMID 35945940, 2022). "We found that NAC pretreatment could inhibit the expression of platelet NLRP3 and cleaved caspase-1 as well as platelet activation and thrombocytopenia in HS rats, indicating that ROS could activate NLRP3 inflammasome in platelets and may be invovled in thrombocytopenia." (PMID 35945940, 2022). "HMGB1 also boosts NLRP3 inflammasome and its adaptor molecule ASC via activating TLR4/ROS signaling, resulting in platelets pyroptosis and thrombocytopenia." (PMID 37063905, 2023). "Animal experiments further revealed that treatment with the Nlrp3 inflammasome inhibitor OLT1177 markedly ameliorated DENV- and rEIII-induced thrombocytopenia in wild-type mice." (PMID 33995345, 2021). "To investigate whether HS-activated NLRP3 inflammasome mediates platelet activation and thrombocytopenia, we injected rats i.p. with MCC950, a specific inhibitor of the NLRP3 inflammasome, before the rats subjected to heat stress." (PMID 35945940, 2022). "Blockages of EIII-induced platelet signaling using the competitive inhibitor chondroitin sulfate B or selective Nlrp3 inflammasome inhibitors OLT1177 and Z-WHED-FMK markedly ameliorated DENV- and EIII-induced thrombocytopenia, platelet activation, and cell death." (PMID 33995345, 2021).
Thrombocytopenia (continued). "Although DENV-induced platelet pyroptosis has not been clearly characterized, Nlrp3 inflammasome-mediated inflammation has also been reported in DENV-stimulated platelets and DENV-induced thrombocytopenia and coagulopathy." (PMID 33995345, 2021).
aortic aneurysm (9 papers, 2020 to 2024). A ruptured aneurysm located in the wall of the proximal portion of the descending aorta proceeding from the arch of the aorta. "Upregulation of the protective Nrf2 antioxidant system and reduction in the NLRP3 inflammasome represents a novel and promising approach to aortic aneurysm treatment; however, clinical efficacy has yet to be established." (PMID 38275364, 2023). "The NLRP3 inhibitor MCC950 effectively prevented aortic aneurysm and dissection induced by AngII in mice." (PMID 35211530, 2022). "Although the direct contribution of the NLRP3-Caspase-1 inflammasome to MMP-9 activation remains to be demonstrated in human aortic aneurysms, targeting this pathway with MCC950 is a promising approach for preventing aortic destruction." (PMID 34572082, 2021). "Similar to aortic aneurysms, the NLRP3 inflammasome is also the most widely investigated inflammasome in aortic dissection in human tissue samples." (PMID 34572082, 2021). "Similarly, in aortic aneurysm and dissection models, suppressing the expression of NLRP3 inflammasome components while simultaneously enhancing elastin protein expression has been observed." (PMID 38992615, 2024). "Western blotting results revealed that NLRP3, MMP2 and MMP9, which induced the degradation of extracellular matrix (ECM), were dramatically increased in the human and mouse aortic aneurysm tissues compared with non‐aneurysmal tissues." (PMID 39601144, 2024).
arthropathy (9 papers, 2014 to 2025). Any disorder of the joints. "The NLRP3 inflammasome is associated with inflammatory and chronic diseases, including bone and joint diseases." (PMID 35628185, 2022). "For example, Snouwaert and colleagues observed that mutation in the NLRP3 gene caused arthropathy and OP in an NLRP3 gene humanized mice model." (PMID 36553538, 2022). "Neutrophilic skin or joint disease favors assessment with IL-17/23 panels, while crystal arthropathies or recurrent inflammatory flares warrant IL-1β, urate, and NLRP3 inflammasome profiling." (PMID 41440484, 2025). "It is known that the activation of the NLRP-3 inflammasome and the production of IL1-β play important roles in the pathophysiology of hydroxyapatite-associated arthropathy." (PMID 38397865, 2024). "In this review, we focus on the current understanding of the molecular mechanisms of inflammasomes and review the role of the NOD-like receptor family, pyrin domain-containing 3 (NLRP3) inflammasome in the pathogenesis of bone and joint diseases." (PMID 35628185, 2022). "The NLRP3 inflammasome is involved in the pathogenesis of bone and joint diseases by affecting inflammation, bone resorption, and bone formation." (PMID 35628185, 2022). "Chemotherapeutic inhibition of the NLRP3 inflammasome was recently shown to inhibit CHIKV arthropathy in a mouse model; the current study, therefore, confirms this pathway as a potential drug target in humans." (PMID 31211814, 2019). "Further studies and clinical trials might clarify the efficacy of these inhibitors and lead to the development of NLRP3 inflammasome inhibitors for the treatment or prevention of bone and joint diseases." (PMID 35628185, 2022). "This review highlights the current understanding of the activation and function of the NLRP3 (NOD-like receptor family, pyrin domain-containing 3) inflammasome in bone and joint diseases." (PMID 35628185, 2022).
cardiac arrest (9 papers, 2015 to 2025). Cessation of breathing and/or cardiac function. "Inhibiting NLRP3 activation reduces the inflammation associated with poor outcomes in rodent models of brain injury associated with cardiac arrest." (PMID 32466385, 2020). "In this study, we aimed to investigate the effect of NAC on post-resuscitation myocardial dysfunction in a cardiac arrest rat model, and whether its underlying mechanism may be linked to ROS and NLRP3 inflammasome-induced pyroptosis." (PMID 32782443, 2020). "Our data showed that cardiac arrest induced microglial pyroptosis and consequential neuroinflammation, mediated by the activation of NLRP3 inflammasome." (PMID 32703306, 2020). "Results from qRT-PCR showed that the mRNA level of NLRP3 was significantly upregulated after cardiac arrest, with a peak at the 12th hour." (PMID 32703306, 2020). "As shown in adult animal models, TH reduces NLRP3 activation and microglia activation after traumatic brain injury or cardiac arrest." (PMID 33123073, 2020). "In this study, by using a rat model of asphyxial cardiac arrest and cardiopulmonary resuscitation, we demonstrate that NLRP3 inflammasome-mediated microglial pyroptosis is critically involved in the development of post-cardiac arrest brain injury." (PMID 32703306, 2020). "In summary, we provide evidence that cardiac arrest induces the assembly of NLRP3 inflammasome, which triggers microglial pyroptosis and consequential neuroinflammation and ultimately aggravates brain injury." (PMID 32703306, 2020). "The elevated expression of NLRP3 and cleaved caspase-1 were further confirmed by immunofluorescent staining at 12 h after cardiac arrest, along with ASC, another key molecule involved in the assembly of inflammasome." (PMID 32703306, 2020). "To further test the role of NLRP3 inflammasome and correlated microglia pyroptosis in post-cardiac arrest brain injury, we targeted the NLRP3 with a highly selective inhibitor MCC950." (PMID 32703306, 2020). "To further verify the role of NLRP3 inflammasome in mediating post-cardiac arrest microglial pyroptosis and its consequential brain injury, we used a selective inhibitor Ac-YVAD-cmk to target caspase-1, the canonical executor of pyroptosis." (PMID 32703306, 2020). "To validate the role of NLRP3 inflammasome-mediated pyroptosis in global myocardial I/R injury, we established a cardiac arrest model in SD rats." (PMID 32782443, 2020). "Taken together, these findings imply that cardiac arrest activates the assembly of NLRP3 inflammasome in microglia, which leads to the self-cleavage of caspase-1 and triggers microglial pyroptosis." (PMID 32703306, 2020). "In conclusion, NAC improves post-resuscitation myocardial dysfunction and prolongs the duration of survival by partly inhibiting NLRP3 inflammasome-induced pyroptosis in a rat model of cardiac arrest." (PMID 32782443, 2020). "Our results showed that, in a rat model, successful resuscitation from cardiac arrest resulted in microglial pyroptosis and consequential inflammatory infiltration which was mediated by the activation of NLRP3 inflammasome." (PMID 32703306, 2020). "In this study, we established a cardiac arrest model and detected NLRP3 inflammasome and GSDMD in myocardial tissues after global myocardial I/R injury." (PMID 32782443, 2020). "We detected distinct expression patterns of the investigated PRRs, with significant upregulation of monocyte NLRP3 mRNA levels in the first and the second blood sampling after cardiac arrest." (PMID 27260481, 2016). "Our findings directly demonstrate the differential regulation of monocyte TLR expression and function in immediate survivors of cardiac arrest and implicate the NLRP3 inflammasome as a potential downstream mediator of the inflammatory response during PCAS." (PMID 27260481, 2016). "Similar to our findings on TLR expression, the upregulation of NLRP3 was restricted to the early phase after cardiac arrest." (PMID 27260481, 2016).